NFATC1 (nuclear factor of activated T cells 1)
Diseases named in the same sentence as NFATC1 in open-access papers (continued):
Sharing a sentence is not in itself a finding about the gene and the disease.
Yersinia infection (1 paper, 2024). "From the KEGG map of Yersinia infection, it is evident that significant methylation changes in VAV3, TBK1, and NFATC1 subsequently influence the downstream interferon response and immune cell response." (PMID 38886689, 2024).
tumor (120 papers, 2010 to 2026). "Despite the importance of the NFAT family in the immune response, recent studies have indicated that activation or overexpression of NFATc1 in human solid tumors and hematological malignancies is associated with tumor progression." (PMID 37121974, 2023). "Mechanistically, the KRAS status determines the transcriptional consequences of EZH2-dependent targeting of the NFATc1 gene, encoding for an inflammatory tumor-progressive transcription factor." (PMID 35884510, 2022). "We thereby demonstrated that the loss of PRC2 repressive activity can drive aggressive BLBC tumor cell phenotypes by promoting NFATc1 expression." (PMID 35016723, 2022). "An analysis related to the KEGG pathways also revealed enrichment in genes that belong to cancer-associated pathways in the tumour cells, compared to their NFATc1- knockdown equivalent, including several associations with metabolism." (PMID 34572796, 2021). "In our experiments, we confirmed that deletion of CABIN1 enhances BCR-induced NFAT reporter activity, gene expression, and is associated with constitutive presence of NFATc1 in the nucleus of the primary OAMZL tumor cells." (PMID 35528192, 2021). "A recent study found that NFATc1-deficient cytotoxic T cells showed reduced cytotoxicity against tumor cells." (PMID 34917508, 2021). "RCAN1.4 loss promoted tumour metastasis to bone and brain, and its overexpression inhibited tumour growth by blocking the calcineurin-NFATc1 pathway." (PMID 32771023, 2020). "In NFATc1 knockdown tumors, P-S treatment caused a 62.8% reduction in tumor volume compared to the vehicle (p=0.0005)." (PMID 24284479, 2014). "In addition, NFATC1 was significantly higher in tumor tissues than in benign uroepithelium, and high NFATC1 expression was significantly associated with poor prognosis." (PMID 38910160, 2024). "Therefore, NFATC1 induction by EZH2 loss is implicated in increased tumor aggressiveness and progression in BLBC patients." (PMID 34845197, 2021). "Immunohistochemistry detected nuclear/cytoplasmic NFATc1 signals in 14 (21.5%)/34 (52.3%), respectively, of 65 muscle-invasive bladder carcinomas and showed that patients with nuclear NFATc1-positive tumor had a significantly higher risk of disease progression (P = 0.006)." (PMID 25638160, 2015). "Our study demonstrates that SMAD4 loss enables NFATc1 to drive STAT3 expression, creating a dependency that fuels tumor progression." (PMID 40856537, 2026). "Strategies combining NFATc1 and c-Jun inhibitors with immunotherapy are being explored to enhance anti-tumor immune responses and improve treatment outcomes in cancer patients." (PMID 40688507, 2025). "NFATc1 was shown to be frequently activated in TNBC as evaluated in tumor tissues from patients, and nuclear localized NFATc1 in TNBC cells was reported to be important for cell migration." (PMID 39436410, 2025). "In various cancers, NFATc1 promotes tumor growth and survival by regulating genes involved in proliferation, angiogenesis, and immune suppression." (PMID 40688507, 2025). "In cancer, NFATc1 can influence tumor growth and progression by regulating the expression of genes involved in cell proliferation and survival." (PMID 40688507, 2025). "Our study elucidates a novel mechanism by which NFATc1 reprograms tumor metabolism and proposes a promising antitumor strategy targeting this pivotal regulatory pathway." (PMID 41203626, 2025). "NFATc1 and c-Jun also play important roles in cancer progression, particularly within the tumor microenvironment where they contribute to immune evasion, metastasis, and resistance to therapy." (PMID 40688507, 2025). "In contrast, the FPR3/NFATc1/NOTCH3 axis exerts tumor-suppressive effects in diffuse-type GC by modulating calcium flux: FPR3 activation restricts NFATc1 nuclear translocation, downregulating NOTCH3-AKT/mTOR signaling and suppressing stemness." (PMID 40977684, 2025).
tumor (continued). "So, we utilized NIFE to inhibit NFATc1 and demonstrated that it exerts anti-tumor effects by suppressing both the NFATc1/NADK and NFATc1/MDM2 signaling pathways." (PMID 41203626, 2025). "NFATC1 increased BLCA to promote tumor cell growth/colony formation and also promoted tumor migration and invasion by increasing expression of MMP2 and MMP9." (PMID 38910160, 2024). "The miR-124-3p derived from hBMSCs inhibits tumor growth both in vivo and in vitro via downregulation of the NFATc1/cMYC pathway." (PMID 37248542, 2023). "When we suppressed the signaling transfer through this cascade by inhibitors of SYK, BTK and PI3 kinases, i.e. by P505-15, ibrutinib and wortmannin, respectively, in Nawalma tumor cells, we observed the relocation of nuclear NFATc1 into cytosol." (PMID 37546418, 2023). "In our clinical data analysis, increased NFATc1 expression was correlated with advanced tumor stage, a high IPI score and poor prognosis in DLBCL patients." (PMID 37248542, 2023). "Confocal microscopy indicated that these tumor cells still expressed NFATc1 proteins, although at reduced levels and in part in cytosol." (PMID 37546418, 2023). "Surprisingly, in human BL and Ramos tumor cells the expression level of NFATc1 mRNA was as high as in primary human B cells, and the majority of NFATc1 transcripts was driven by the P1 promoter." (PMID 37546418, 2023). "We previously demonstrated that NFATc1 can directly upregulate cMYC gene expression by binding to the cMYC promoter; this upregulation is closely related to the growth and survival of tumor cells." (PMID 37248542, 2023). "In conclusion NFATc1 was suppressed both in Hodgkin tumor cells and inflammatory cells surrounding the tumor cells." (PMID 34181355, 2021). "Correspondingly, serum CTX-1 level and the expression of osteoclast signature genes Acp5, Ctsk, Mmp9, and Nfatc1 in mice bearing SCP28/Sh-miR-21 tumors were comparable with tumor-free mice." (PMID 33391543, 2021). "Known as an essential transcription factor in many physiologic systems comprising immune cells, including in regulation of PD-1 activation, nuclear factor of activated T cell (NFATc1) has roles in tumor microenvironment." (PMID 34181355, 2021). "These cells were located far from tumor cells, while small lymphocytes surrounding tumor cells have only cytoplasmic expression of NFATc1." (PMID 34181355, 2021). "Numerous downstream effectors of EGFR signaling bypassing activated KRAS and promoting tumor progression have been identified, including NFATc1 and c-MYC." (PMID 34070180, 2021). "Patients suffering from advanced-stage NSCLC exhibit a progressive decrease of NFATc1 in tumor cells and TILs decrease progressively." (PMID 34707601, 2021). "Accordingly, the expression of osteoclast differentiation and function genes Acp5, Ctsk, Mmp9, and Nfatc1 was much higher in the bone of tumor-bearing mice than those in the bone of tumor-free mice." (PMID 33391543, 2021). "Future study is needed to unravel how the precise mechanisms control the silencing of NFATc1 in tumor microenvironment of HL." (PMID 34181355, 2021). "Our data showed that there were only few small lymphocytes expressed nuclear NFATc1, but these cells were situated far from tumor cells." (PMID 34181355, 2021). "Beside these considerations, NFATc1 has a prominent function in T-cells induction and is necessitated for the correct activation of cytotoxic T cells during tumor cell clearance." (PMID 34845197, 2021). "Up to now, the relationship between NFATc1 and miRNA processing in tumor progression remains little known." (PMID 31823518, 2020). "Our data suggest that NFATc1 and especially NFATc3 are overexpressed in tumour samples compared with normal tissue, while NFATc2 is minimally expressed." (PMID 31249342, 2019).
tumor (continued). "Together, these data not only confirm the positive role of NFATc1 in the regulation of tumor cell proliferation but also suggest that NFATc1 at least partially interferes with the tumor growth-inhibiting function of TGFβ." (PMID 31171768, 2019). "NFATc1 has been shown to promote tumor progression in pancreatic cancer, melanoma, and breast cancer, and to be implicated in lymphangiogenesis." (PMID 30984176, 2019). "The isoform NFATc1 seems to act as an oncogene as a constitutively active form of NFATc1 is able to induce neoplastic transformation of fibroblast cells, whereas the isoform NFATc2 rather seems to act as a tumor suppressor." (PMID 30984176, 2019). "Here, staining for NFATC1 revealed a high number of osteoclasts at the intra‐tibial tumor/bone interface; in addition, the amount of RANKL in cell culture supernatants and mouse serum increased." (PMID 31372592, 2019). "Chk1 inhibitors blocked the proliferation, survival, and migration of tumor cells in vitro and suppressed the development of bone-resorbing osteoclasts by downregulating NFATc1." (PMID 29507695, 2018). "In vitro results showed that PD407824 and PF477736 were potent inhibitors of proliferation and migration of 4T1.2 tumor cells by upregulating cleaved caspase 3 as well as effective suppressors of NFATc1, the master transcription factor of osteoclastogenesis." (PMID 29507695, 2018). "Our results from ΔCam × N3 double-tg mice show the tumour suppressor activity of NFATc1 in the experimental setting of hyperactive Notch, as it prevented T-ALL development despite these mice having constitutive Notch3 signalling." (PMID 27312418, 2016). "HF bulge markers CD34, K15 and NFATc1 were decreased in tumours isolated from both K14ΔNLef1 and K15ΔNLef1 animals when compared with DMBA-treated skin of wild-type mice." (PMID 25608467, 2015). "In a sarcoma model, NFATc1 was also found to be oncogenic, whereas NFATc2 functioned as a tumor suppressor." (PMID 25638160, 2015). "Given the important role of NFATc1 in drug resistance, it represents a novel prognostic factor for predicting drug response and a potential therapeutic target for improving tumor responsiveness to chemo-therapeutic drugs." (PMID 24284479, 2014). "We determined the effect of NFATc1 knockdown or overexpression on the tumor response to P-S in vivo." (PMID 24284479, 2014). "NFATc1 likely mediates drug resistance to P-S and is an unfavorable prognostic factor that predicts poor tumor response." (PMID 24284479, 2014). "Consistent with in vitro findings, NFATc1 expression is an important factor that negatively regulates the tumor responsiveness to P-S in vivo." (PMID 24284479, 2014). "In cancer, disrupting the NFATc1 and c-Jun synergy could impair tumor cell survival and proliferation." (PMID 40688507, 2025). "Furthermore, patients with both CagA expression and nuclear localization of NFATc1 in tumor cells responded to HPE more rapidly than those with either CagA or NFATc1 expression alone, or with no expression of CagA or NFATc1." (PMID 39558403, 2024). "In summary, we found that miR-124-3p derived from hBMSCs could be absorbed by DLBCL cells and inhibit tumor growth both in vivo and in vitro via downregulation of the NFATc1/cMYC pathway." (PMID 37248542, 2023). "In one case (́Group C ́), NFATc1 appeared overexpressed only in a fraction of tumor cells." (PMID 37546418, 2023). "Targeting MDM2/TPSO (translocator protein), MDM2/PKC (protein kinase C), MDM2/NF-kB (nuclear factor-kappa B), MDM2/Bcl-2 (B-cell lymphoma-2) and MDM2/NFAT1 (nuclear factor of activated T-cells 1) had good anti-tumor activity and had the potential to reduce the adverse reactions of MDM2 inhibitors." (PMID 35831864, 2022). "Cytoplasmic expression of NFATc1 was observed in small lymphocytes surrounding tumor cells." (PMID 34181355, 2021). "CD3D and NFATC1 were the common genes in the three tumor data sets." (PMID 34794456, 2021).
tumor (continued). "Activated NFATC2 in fibroblast NIH3T3 cells may block the cell cycle and inhibit cell transformation, showing potential to suppress the tumor, while activated NFATC1 promotes cell proliferation and malignant transformation of carcinogenic properties." (PMID 34309232, 2021). "Finally, we demonstrate that blocking peptides competitively inhibit the effect of DYRK1A on NFATC1, clearly reducing NFATC1 protein and impairing tumor migration." (PMID 34309232, 2021). "In summary, NFATC2 acts as a tumor suppressor, whereas NFATC1 exhibits oncogenic activity." (PMID 34309232, 2021). "NFATc1 may contribute to the molecular pathways entailed in tumor microenvironment of HL, which, then both promote to HL progression and worsen prognosis." (PMID 34181355, 2021). "The expression of PD-1 receptor driving in decreased activation of NFATc1, thereby, this mechanism is one factor that was most likely led to down regulation of NFATc1 in lymphocytes surrounding tumor cells in our samples, yet the exact mechanism is still unclear." (PMID 34181355, 2021). "These datasets were in full agreement confirming the up-regulation of NFATc1 in a tumour." (PMID 34572796, 2021). "NFATc1 was suppressed both in Hodgkin cells and inflammatory cells surrounding the tumor cells." (PMID 34181355, 2021). "Importantly, upon EZH2 depletion in PDAC models with EZH2-disentangled, constitutive NFATc1 activation strongly abrogated the tumor-promoting activities of the transcription factor, both in vitro and in vivo." (PMID 34943970, 2021). "Down regulation of NFATc1 in TAMs and Hodgkin cells may result in T cells anergy, thus, promotes tumor progression." (PMID 34181355, 2021). "Remarkably, the combination of NFATc1 inhibition and chemotherapy significantly increased the efficiency of the treatment, demonstrating that NFATc1 plays a critical role during survival of tumor cells to cytotoxic treatments." (PMID 34845197, 2021). "In order to further elucidate the functional and mechanistic consequences of TGFβ signaling in the context of constitutively active NFATc1 we isolated primary PDAC cells from three different tumor-bearing NKC p48 mice (further designated as NKC-II, NKC-VI, and NKC-VIII)." (PMID 31171768, 2019). "Based on the significant tumor-promoting role of NFATc1-dependent transcription in PDAC, we proposed that NFATc1 activity may be associated with a bad prognosis of PDAC patients." (PMID 31171768, 2019). "Importantly, the pro-tumorigenic consequences of NFATc1 activity in PDAC were not only limited to activation of transcriptional programs involved in positive regulation of tumor growth but also comprise the blockade of apoptosis-associated gene signatures." (PMID 31171768, 2019). "Additionally, the levels of TRAF6, BRD4, and NFATc1 expression, IκB-α degradation, and p65 nuclear translocation were higher in blood mononuclear cells from tumor samples than in those from normal group at basal levels." (PMID 30455393, 2019). "However, combined TGFβ treatment and NFATc1 depletion resulted in a tremendous abrogation of tumor-promoting gene signatures and functions." (PMID 31171768, 2019). "Consistent with our findings from human cancer, NFATc3 is also the dominant isoform among NFAT isoforms (NFATc1-c4) and significantly increased in the tumor bearing tongue compared to normal tongue, suggesting that increased NFATc3 is associated with chemical-induced oral carcinogenesis." (PMID 31040921, 2019). "Consequently, decreased DNA synthesis and abrogated tumor cell proliferation upon TGFβ treatment in primary NKC cells were enforced by additional NFATc1 knockdown." (PMID 31171768, 2019).
tumor (continued). "This suggested that BLV in SCC tumor cells might interact closely with NFATc1, which is an oncogene involved in various functions in cancer." (PMID 30134863, 2018). "The relationship between low expression of NFATc1 and larger tumor size suggests that the decline in NFATc1 expression may help facilitate rapid tumor expansion." (PMID 30085405, 2018). "Furthermore, to understand how NFATc1 regulates downstream proteins to exert its tumor suppressor function, we performed qRT‐PCR analysis to examine candidate downstream genes that have important functions in tumor proliferation, apoptosis, and angiogenesis." (PMID 30085405, 2018). "NFATc1 has oncogenic activity, whereas NFATc2 acts as a tumor suppressor." (PMID 28235034, 2017). "Pretreatment of wild-type CD8+ CTLs with the NFATc1 inhibitor CsA could also downregulate PD-1 expression and enhance anti-tumor therapeutic efficacy." (PMID 25851535, 2015). "Furthermore, NFATc1 inhibitor significantly enhanced the anti-tumor efficacy of oxaliplatin." (PMID 41203626, 2025). "In addition, NFATC1 was significantly higher in tumor tissues than in benign urothelium." (PMID 38910160, 2024). "Interestingly, enhanced tumor growth together with decreased effector memory and CD103+ TRM cells were observed in tumor-bearing lungs of mice with T-cell-specific NFATc1 inactivation, thus highlighting the role of this transcription factor in cytotoxic T-cell immunity and TRM cell tissue retention." (PMID 36305904, 2022). "However, in Hodgkin cells NFATc1 is not expressed caused by epigenetic silenced mechanism, while NF-κB is constitutively active in these tumor cells." (PMID 34181355, 2021). "However, here we would like to know whether NFATc1 may have roles in activation of TAMs CD163+ in tumor microenvironment of HL." (PMID 34181355, 2021). "Therefore, certain mechanisms to reactivate functional NFATc1 in cHL tumor microenvironment may be necessary; hence, the tumor cells are able to be eradicated by patient’s immune mechanisms." (PMID 34181355, 2021). "Therefore, certain mechanisms to reactivate functional NFATc1 in HL tumor microenvironment may be necessary; hence, the tumor cells are able to be eradicated by patient’s immune mechanisms." (PMID 34181355, 2021). "Moreover, GSEA revealed a positive enrichment of cell cycle promoting gene signatures in siCtrl samples predominantly when compared to siNFATc1+TGFβ conditions, suggesting that combined TGFβ treatment and NFATc1 depletion has synergistic impact on reduction of tumor cell proliferation in PDAC cells." (PMID 31171768, 2019). "Hence, we postulate that TGFβ competes with NFATc1 for the regulation of tumor-promoting target genes, for instance, by recruiting chromatin regulatory proteins with opposing consequences on histone acetylation, chromatin accessibility, and subsequent transcriptional activity." (PMID 31171768, 2019). "Together, these results indicate that NFATc1 might function as a tumor suppressor in HCC." (PMID 30085405, 2018). "However, loss of function mutations involving NFAT has not been reported in spontaneous cases of either human or murine T-ALL; thus, the tumour suppressive activity of NFATc1 may be specific to the background of the additional oncogenic events." (PMID 27312418, 2016).